HNF4A (hepatocyte nuclear factor 4 alpha)
Diseases named in the same sentence as HNF4A in open-access papers (continued):
Sharing a sentence is not in itself a finding about the gene and the disease.
Hyperglycemia (25 papers, 2016 to 2025). An increased concentration of glucose in the blood. "Mutations in the HNF1A and HNF4A genes result in pancreatic β-cell dysfunction, which in turn causes hyperglycemia." (PMID 39902162, 2024). "This also demonstrates that abnormalities in HNF4a lead to the loss of pancreatic β-cell function, exacerbating disorders in glucose metabolism, resulting in persistent hyperglycemia, and further intensifying oxidative stress and inflammatory responses within the body." (PMID 40469443, 2025). "Higher blood glucose levels while on DZX treatment could involve a mechanism similar to the dual phenotypic presentation in the HNF1A/HNF4A mutations, switching from hypoglycemia to hyperglycemia." (PMID 39421536, 2024). "Thus, it may be possible that progressive beta cell loss in MKO occurs as a result of impaired beta cell ER function, due to HNF4α absence that together with progressive consequent hyperglycemia further aggravate the ER stress and beta cell loss via induction of ER apoptotic pathways." (PMID 41017587, 2025). "Patients with HNF4A mutations often show reduced glucose-stimulated insulin secretion and hypoinsulinemia-induced hyperglycemia, but without evidence of beta-cell autoimmunity, suggesting a specific dysfunction in beta-cell regulation." (PMID 40149950, 2025). "Macrosomia, in particular, is more frequently associated with HNF4A-MODY due to its impact on fetal insulin secretion, but has also been occasionally reported in HNF1A-MODY, potentially reflecting unrecognized maternal hyperglycemia." (PMID 41367630, 2025). "Specifically, activities of HNF1A and HNF4A were highly increased in hyperglycemia." (PMID 36285680, 2022). "Unlike GCK-MODY, patients with HNF4A gene variants may develop severe hyperglycemia over time, and, thus, may require insulin therapy." (PMID 40149950, 2025). "Of the MODY genes described to date, only hepatocyte nuclear factor-4-alpha (HNF4A; MODY1) and hepatocyte nuclear factor-1-alpha (HNF1A; MODY3) mutations may result in a biphasic phenotype of hypoglycemia in early life and hyperglycemia in later life." (PMID 32670997, 2020). "Clinical presentation of patients with HNF4A MODY is similar to that of patients with HNF1A MODY, namely hyperglycemia appearing in adolescence or early adulthood (before 25 years of age), with gradual deterioration due to progressive beta cell dysfunction." (PMID 39408828, 2024). "In contrast to the severe and progressive beta cell defect seen in HNF1A and HNF4A MODY, patients with GCK‐related fasting hyperglycaemia retain their counter‐regulatory response to an increase in blood glucose concentration." (PMID 35445424, 2022). "Although both studies reported impaired glucose tolerance in Hnf4A deficient mice, along with defects in GSIS, neither study observed sustained hypoinsulinemic hyperglycemia – the defining symptom that brings MODY1 patients to the clinic." (PMID 27185732, 2016). "The clinician should review the prognosis of the condition and potential changes in medical management (e.g., no treatment in GCK- hyperglycemia and sulfonylurea treatment with HNF1A and HNF4A monogenic diabetes." (PMID 37794142, 2023).
Cirrhosis (23 papers, 2014 to 2026). A chronic disorder of the liver in which liver tissue becomes scarred and is partially replaced by regenerative nodules and fibrotic tissue resulting in loss of liver function. "HNF4α dysfunction is associated with multiple liver disorders, such as liver fibrosis and cirrhosis, alcoholic liver disease and non-alcoholic fatty liver disease (NAFLD)." (PMID 39261648, 2024). "Upstream regulator analysis identified HNF-4α and IL-6 as the most important regulators underlying the observed serum proteome changes in patients with decompensated cirrhosis." (PMID 36652164, 2023). "Loss of HNF4α expression is associated with liver cirrhosis and reintroduction of HNF4α can reverse cirrhosis, underscoring the essential nature of this transcription factor to overall liver function." (PMID 37600688, 2023). "The early silencing of miR-122 and HNF4A increases the risk for HCC development in cirrhosis." (PMID 31547152, 2019). "In rats with advanced cirrhosis, reduction in HNF4α expression correlates with worsening of liver function." (PMID 39524892, 2024). "Immunohistochemical and biochemical tests confirmed reduced HNF4α and transferrin protein levels in individuals with cirrhosis." (PMID 33593348, 2021). "Our study also provides an explanation why HNF4A targeted protein expression is decreased in cirrhosis due to severe hepatic stress response." (PMID 31547152, 2019). "Our data is supported by studies showing that mRNA and protein expression levels of HNF4A decreased severely patients with cirrhosis." (PMID 31547152, 2019). "Many recent publications claim that the expression level of HNF4A and its target genes are impaired in cirrhosis and diminished in HCC." (PMID 31547152, 2019). "In conclusion, our data indicate that hepatic pro-survival UPR signaling suppresses the liver-specific HNF4A and its downstream target miR-122 in cirrhosis." (PMID 31547152, 2019). "In a rat model of cirrhosis, HNF4α significantly suppresses EMT of hepatocytes and alleviates dimethylnitrosamine-induced fibrosis." (PMID 25303175, 2014). "In contrast, patients with compensated cirrhosis and preserved synthetic function did not have a functional HNF4α deficiency." (PMID 41109667, 2026). "Acute or chronic cellular injury resulted in decreased HNF4α loss, due to inflammatory pathways such as NF-κB that induce endoplasmic reticulum stress and impair HNF4α recruitment for normal metabolic functions, as observed in models of chronic hepatocyte injury, cirrhosis, and colitis." (PMID 37974020, 2023). "To evaluate whether FABP1, SGK2, and HNF4A related to cirrhosis and HCC, we examined the methylation levels of these gene using the GSE60753 dataset." (PMID 35655171, 2022). "Lipid nanoparticle-mediated HNF-4α gene (HNF4A) ameliorates fibrosis and cirrhosis." (PMID 36435860, 2022). "The protein hepatocyte nuclear factor 4 alpha (HNF4α) has been identified as a central gene in the pathogenesis of nonalcoholic steatohepatitis (NASH), a subset of NAFLD characterized by inflammation with increased risk for cirrhosis and HCC over NAFLD." (PMID 36473131, 2022). "Network 2 was persistent in viral hepatitis, cirrhosis, and HCC, with three potential hub genes (FABP1, SGK2, and HNF4A)." (PMID 38302914, 2024). "In contrast to healthy livers, ASH cirrhosis patients and most other patients with severe liver disease showed CK19+ cells with nuclear HNF4α staining." (PMID 36914834, 2023). "Three weeks after the induction of cirrhosis, MSCs modified by HNF-4α overexpression adenoviruses (HNF-4α-MSCs) were injected into the mice's tail vein." (PMID 37226279, 2023). "Furthermore, alterations in the acetylation pattern of HNF4A have been observed in human decompensated hepatocytes, notably in conditions like nonalcoholic steatohepatitis (NASH) and alcohol-induced Laennec’s cirrhosis in explanted livers." (PMID 41326348, 2025).
Cirrhosis (continued). "Hepatic HNF4α is downregulated in NAFLD and in advanced cirrhosis at the expression level, transcribed from an alternative promoter (P2 promoter) in AH, and accumulates in the cytoplasm due to reduced acetylation in advanced cirrhosis." (PMID 39261648, 2024). "The expression of HNF4A is decreased in NAFLD, as well as in viral hepatitis and cirrhosis." (PMID 35655171, 2022). "The suggested expression changes in HNF4A and IL6 mRNA, but not HNF1A were validated in liver tissue of patients with cirrhosis as compared to nine controls without." (PMID 36652164, 2023).
liver disease (22 papers, 2012 to 2025). "A progressive loss of HNF4A activity is observed in liver diseases (SLD) compared to HCC." (PMID 38157373, 2023). "Notably, the syndromic condition including CHI, renal and hepatic disease has exclusively been reported in patients with the same HNF4A missense variant, p.Arg63Trp (R63W, also known as R76W or R85W)." (PMID 37065762, 2023). "In addition, the transfer of genes coding for important transcription factors regulating hepatogenesis, such as HNF4α and forkhead box protein (Foxa2), was investigated in the context of liver diseases in association with stem cell therapy." (PMID 32974331, 2020). "One of these factors, HNF4α, plays a major role in coordinating hepatic gene expression and maintaining lipid homeostasis, explaining that its loss-of-function is associated with metabolic disturbances and liver disease." (PMID 32982982, 2020). "It was reported that HNF-4α has less expression in liver disease conditions; therefore, researchers suggested overexpression of HNF-4α can increase the curative effect of this factor on liver damage." (PMID 37226279, 2023). "We now identified HNF4α+CK19+ BECs in 11 different liver disease indications, whereas we only found negligible amounts in healthy patients." (PMID 36914834, 2023). "Mechanistically, in early liver disease with fibrosis, liver matrix stiffness and cytoskeletal tension inhibit the hepatocellular HNF4-α transcriptional network." (PMID 36652164, 2023). "In advanced liver disease, such as alcohol-related liver failure, hepatic activity of the liver-enriched transcription factor HNF-4α is severely inhibited, reducing hepatic expression of cytochrome P450 enzymes, apolipoproteins, and aldolases." (PMID 36652164, 2023). "Critical homeobox nuclear factor family members that are normally downregulated in severe liver disease such as Hnf4a and Hnf1b were, however, unchanged." (PMID 36232721, 2022). "HNF4A-MODY patients also exhibit liver disorders such as increased LDL cholesterol levels owing to altered expression of apolipoprotein genes." (PMID 34732735, 2021). "Here, we studied the mechanisms regulating transferrin production in individuals with advanced liver disease and AH and show that serum transferrin levels reflect the hepatic activity of HNF4α." (PMID 33593348, 2021). "The correlation between hepatic HNF4A and transferrin mRNA levels was also seen in advanced liver disease." (PMID 33593348, 2021). "The existence of a positive correlation between ACOX2 and HNF4A expression in inflammatory liver diseases supports the hypothesis that ACOX2 expression can be controlled by HNF4α, which is consistent with the predominant ACOX2 expression in hepatocytes." (PMID 36552746, 2022). "Moreover, HNF4α activity is diminished in multiple liver disorders including AH and decompensated liver cirrhosis and is likely crucial for their pathogenesis." (PMID 33593348, 2021). "HNF4α-overexpressing hepatic progenitors may serve as an alternative cell source for transplantation to treat liver diseases." (PMID 28807057, 2017). "However, the relationship of the level of HNF4α and HNF3β with the severity of HBV-infected liver diseases is unclear." (PMID 22257755, 2012).
metabolic syndrome (19 papers, 2011 to 2025). A cluster of metabolic risk factors for CARDIOVASCULAR DISEASES and TYPE 2 DIABETES MELLITUS. "Indeed, variants in the HNF4α P2 promoter have been associated with increased risk of metabolic syndrome and late-onset diabetes." (PMID 41167395, 2025). "If stored cord blood was available, the methylation levels of proopiomelanocortin (POMC), the melanocortin 4 receptor (MC4R), and hepatocyte nuclear factor 4 alpha (HNF4a; associated with metabolic syndrome) were assayed in participants in check-up examinations at the ages of 7-9 years." (PMID 33677859, 2021). "Association between HNF4A polymorphisms and metabolic syndrome: odds ratio." (PMID 25671620, 2015). "Association between HNF4α haplotypes and metabolic syndrome." (PMID 25671620, 2015). "The present study aimed to investigate the relationship between HNF4A genetic variants and the presence of metabolic syndrome (MetS) in a pediatric French Canadian population, and to explore their association with metabolic parameters, for instance levels of blood glucose, insulin and lipids." (PMID 25671620, 2015). "We aimed to investigate the relationship between HNF4A genetic variants and the presence of metabolic syndrome (MetS) and metabolic parameters in a pediatric population." (PMID 25671620, 2015). "HNF-4α dysfunction has been observed in mature onset diabetes of the young, T2D, dyslipidemia, and the metabolic syndrome." (PMID 27011261, 2016). "The data strongly support a beneficial role of BBR in improving glucose and lipid homeostasis and suggest that the HNF-4α regulated miR122 pathway is a potential therapeutic target for treatment of T2D with accompanying dyslipidemia." (PMID 27011261, 2016). "Since the whole-body HNF4α knockout is embryonic lethal and a liver-specific knockout results in death at six weeks of age due to dyslipidemia, high serum bile acid levels and ureagenesis defects, an HNF4α exon swap mouse model was developed to examine the effects of the HNF4α isoforms in vivo." (PMID 37600688, 2023). "Taken together, dyslipidemia in diabetic nephropathy mice was ameliorated by the downregulation of HNF4A and activation of AMPK and SIRT1, which could be related to abnormal lipid metabolism in renal podocytes in diabetic nephropathy." (PMID 35480869, 2022).
Hypoglycemia (15 papers, 2008 to 2024). A decreased concentration of glucose in the blood. "This is inconsistent with the increased birth weight and transient neonatal hypoglycemia of most HNF4A mutation carriers." (PMID 37711893, 2023). "When her son presented with hypoglycemia in the neonatal period, he underwent routine genetic testing for hyperinsulinemic hypoglycemia, which revealed a specific mutation in HNF4A." (PMID 28693455, 2017). "Inactivation of the HNF4A gene in mice resulted in hyperinsulinaemia in utero and overt hypoglycaemia in early life." (PMID 38933924, 2024). "Because of the drug history and hypoglycemia symptoms of the proband’s father, they were suspected to have HNF-1A or HNF-4A mutation." (PMID 28105082, 2017).
pancreatic cancer (15 papers, 2012 to 2024). "Herein, we provide several lines of evidence indicating that DNA methylation is responsible for HNF4A loss in pancreatic cancer, and most importantly, we identify the specific promoter loci responsible for direct HNF4A transcriptional regulation." (PMID 39165427, 2024). "Overall, these data demonstrate that HNF4A loss is an early event during pancreatic cancer development, significantly contributing to increased growth and aggressiveness." (PMID 39165427, 2024). "A recent report based on a pancreatic cancer mouse model proposed that HNF4A loss is necessary for the phenotypic switch from a classical to a basal subtype." (PMID 39165427, 2024). "This aligns with previous findings associating HNF4A knockdown with an upregulation of WNT pathway signaling molecules, and HNF4A loss drives metabolic reprogramming at an early stage of pancreatic cancer progression." (PMID 38645221, 2024). "To evaluate the functional role of HNF4A in pancreatic cancer, we performed a series of in vitro loss and gain of functional assays using 4 different pancreatic cancer cell lines." (PMID 39165427, 2024). "In accordance with our data from the KPC animal model, HNF4A expression is significantly suppressed from stage I indicating that HNF4A loss is an early event in human pancreatic cancer." (PMID 39165427, 2024). "Taken together, these data suggest that HNF4A is a tumour suppressor in pancreatic cancer and its loss induces carcinogenic cellular properties including increased growth, colony formation, and invasiveness." (PMID 39165427, 2024). "HNF4A locus susceptibility to methylation, in pancreatic cancer, indicated possible causative mediation effects on gene expression." (PMID 39165427, 2024). "Expression analyses in patients indicate the methylation-associated suppression of HNF4A expression in pancreatic cancer tissues." (PMID 39165427, 2024). "Finally, this study using tissues from 3 different cohorts of patients demonstrates that HNF4A loss is an early event in pancreatic cancer and correlates with poor patient survival." (PMID 39165427, 2024). "Having shown HNF4A loss in one cohort of pancreatic cancer patients (Stanford, USA) and one commercially available TMA, we sought to discern whether this event has any clinical significance." (PMID 39165427, 2024). "We next employed 4 different sets of experiments, to address whether DNA methylation is the mechanism underlying HNF4A decreased expression in pancreatic cancer." (PMID 39165427, 2024). "Furthermore, HNF4A loss in pancreatic cancer also drives metabolic reprogramming and correlates with a metabolic switch to dependence on glycolytic activity, suggesting a more widespread role for HNF4A in this context." (PMID 36153371, 2022). "We have analysed HNF4A expression, through immunohistochemistry, in a discovery cohort of 168 pancreatic cancer and 38 normal tissues (QMC cohort, UK)." (PMID 39165427, 2024). "HNF4A silencing, mediated by promoter DNA methylation, drives pancreatic cancer development and aggressiveness leading to poor patient survival." (PMID 39165427, 2024). "Using 3 independent cohorts of patients, we found a significant suppression of HNF4A in pancreatic cancer." (PMID 39165427, 2024). "To validate the HNF4A methylation microarray data, we performed targeted bisulfite sequencing in pancreatic cancer cells." (PMID 39165427, 2024). "In support of these data, immunohistochemical analysis showed HNF4A suppression in pancreatic cancer." (PMID 39165427, 2024). "In vitro loss and gain of functional assays uncovered a tumour suppressive role for HNF4A, further supported in mouse models of pancreatic cancer." (PMID 39165427, 2024). "In accordance, HNF4A restoration significantly impaired pancreatic cancer cell invasiveness (Figure A22)." (PMID 39165427, 2024). "Apart from recent studies focusing on HNF4A dysregulation, its functional role in pancreatic cancer is far from clear." (PMID 39165427, 2024).